IL4R (interleukin 4 receptor)
Diseases named in the same sentence as IL4R in open-access papers (continued):
Sharing a sentence is not in itself a finding about the gene and the disease.
tumor (continued). "Our data suggest that it is likely that IL4Rα expression in other cell types (non-immune cells), as well as the cytokines and cells infiltrated into the tumor microenvironment, replace the pro-tumoral activity mediated by TAMs." (PMID 34681866, 2021). "Interleukin and chemokine receptors IL4R and CXCR2—pivotal molecules in alternative macrophage activation and immunosuppression—show significantly higher expression in the NE-low tumor phenotype compared to NE-high (8.71 ± 2.16 vs. 7.88± 1.84, p = 0.009 and 5.5 ± 1.02 vs. 3.83 ± 2.11, p < 0.001)." (PMID 34200100, 2021). "Nonetheless, the expression of inhibitory and suppressive markers, including genes for IL-4R, IL-10, IL-6, VEGFA, CCL2 and IL-1β, were mostly expressed by cluster 0, suggesting that these cells had a tumor-promoting and immune-suppressing functions, which resemble MDSC-like cells." (PMID 34025646, 2021). "Therefore, when considering the oncogenic role of JAK2 and tumor-suppressive role of FOXO3, nuclear localization of IL4Rα/IL13Rα1 exerts its role by involving JAK2-FOXO3 interaction in the progression of STSs." (PMID 33419470, 2021). "Anti-VCAM-1 and anti-IL4Rα DNA aptamers specific to VCAM-1 and IL4Rα receptors that are overexpressed in 4T1 tumor-bearing mice could be used as potential biomarker for both diagnostic and therapeutic applications in cancer biology." (PMID 32751068, 2020). "So, this result verified that cellular binding depended more on the presence of IL-4R on the surfaces of tumor cells than on nonspecific penetration by Tat or the effect of hyperthermia." (PMID 31952530, 2020). "Mechanistically, IL4Rα and IL13Rα1 could increase JAK2 signaling pathway and suppress tumor-suppressive activity of FOXO3." (PMID 31540495, 2019). "To characterize the mutation status and gene expression levels of the cytokines IL-4 and IL-13, their receptors IL-4Rα, IL-13Rα1/2, and the oncogenes c-Met and EGFR, we performed exome and RNA-seq analysis on DIPG tissues (38 tumor exome, 26 normal exome, 28 tumor RNA, 18 normal RNA)." (PMID 29621254, 2018). "A similar result was obtained when a macrophage signature comprising a subset of eight widely used markers (CD14, CD105, CD11b, CD68, CD93, CD33, IL-4R and CD163) for the mononuclear phagocyte system was used to identify tumours highly infiltrated by macrophages." (PMID 29921315, 2018). "Tumor formation was not altered and all injected sites developed tumors irrespective of IL-4Rα expression." (PMID 28350325, 2017). "Significant activation of DNA binding activity of STAT6, phosphorylation of STAT6 as well as IL-4, IL-4Rα and p21 expression were found in the tumor tissues of IL-4 mice compared to non-transgenic mice." (PMID 26993600, 2016). "The apoptotic cells were capable of directly activating macrophages in vitro toward a pro-tumor phenotype (and away from an anti-tumor pro-inflammatory state) in the absence of IL-4Rα." (PMID 25702581, 2015). "We observed that splenic MDSC induction in AOM-induced tumour-bearing animals was absent in IL-4Rα−/− mice (available at Carcinogenesis Online)." (PMID 23784081, 2013). "Lack of tumour cell IL-4Rα signalling alone in a WT host resulted in reduced tumour cell proliferation but no change in AI." (PMID 23784081, 2013). "In contrast with the effect of IL-4Rα deletion on ACF multiplicity, lack of IL-4Rα-mediated signalling did not promote macroscopic tumour development in female mice." (PMID 23784081, 2013). "The binding of tumor cells by [AP1-V12]6 polymer was remarkably reduced in a concentration-dependent manner by pre-incubation with different concentrations (1, 5 and 10 μg/mL) of anti-IL-4R antibody." (PMID 24339977, 2013). "In that study, the IL-4Rα signaling contributed to tumor formation rather than to being protective against tumors." (PMID 24403255, 2013). "In addition, the cytokine receptors IL4R and IL7R were found to be higher expressed in VEGFA165 tumours implicating the possibility of paracrine effects." (PMID 22045186, 2011).
tumor (continued). "Although targeting of IL-4R in MM has not yet been pursued clinically, expression studies showed moderate to strong staining in 13 of 13 patient-tumour samples, proving it to be a logical therapeutic target." (PMID 19755995, 2009). "Additionally, IL4R-Abx increased the M1-macrophage population and CD8+ T-cell/Treg ratio, while decreasing the M2-macrophage and MDSC population in LLC tumor tissues at higher levels than Abx and Ctrl-Abx." (PMID 38646639, 2024). "Notably, the IL‐4R holds significance in the context of TAMs, as its elevated expression on their surface facilitates the binding with IL‐4, thereby promoting TAM polarization towards the M2 phenotype and consequently fostering tumour development." (PMID 38572668, 2024). "Results showed that IL4R-Exo(si/mi) successfully decreased the levels of M2 markers and cytokines, including Arg-1, TFG-β, IL-10, and IL-4 and increased the expression of M1 cytokines, including IL-12 and IFN-γ in the lymphomononculear population of tumor tissues." (PMID 39000385, 2024). "In addition, tumor tissue showed an increase in heparanase, MMP9, PPARγ, and IFNγ, while non-tumor adjacent tissue showed an increase in E-cadherin and COX2 and a decrease in IL-4R." (PMID 36139645, 2022). "This reduction in intracellular cholesterol enhances IL-4 receptor (IL-4R)/STAT6/PI3K signaling in vitro and in vivo, promoting the expression of the typical M2 marker arginase-1 while inhibiting NOS2 and proinflammatory IL-12 expression, thereby promoting tumor progression." (PMID 34876704, 2022). "Therefore, is likely that in LysMcreIL4Rα−/lox-CAC mice the immune response mediated by M1 macrophages was not sufficient to stop tumor growth due to IL4Rα expression and pSTAT6 overactivation in colon tissue." (PMID 34681866, 2021). "Human macrophages in tumor, but not in the spleen or PB, expressed a significant amount of IL-4Rα." (PMID 29456539, 2018). "Third, although the IL4 pathway was significantly enriched in both the tumor progression and chemotherapy signatures, the IL4 gene was not differentially expressed in either of the two comparisons, and the expression levels of two receptors for IL4 (IL4R and IL2RG) were divergent." (PMID 23451142, 2013). "After the critical stage (stage IIB), signaling receptor genes (IL4R) were highly expressed, which might have triggered the phosphorylation of PI3K and AKT proteins and further upregulated the expression of the apoptosis inhibitor BCL2L1 and enhanced tumor cell growth and proliferation." (PMID 38576021, 2024). "Finally, tumor tissue stage I presented lower IL-4R levels than non-tumor adjacent tissue stage I." (PMID 36139645, 2022). "Thus, the absence of IL4Rα did not affect the number of circulating monocytes available to be recruited by tumor cells to the lungs and, consequently, the reduced tumor burden in the lung of IL4Rα−/− mice was not due to a reduction in the availability of circulating monocytes but their function." (PMID 36077870, 2022). "Interleukin-4 (IL4), a key cytokine for Th2 differentiation, binds to IL4R, forming the type I IL4 receptor (IL4R-IL2RG) on lymphoid cells and the type II IL4 receptor (IL4R-IL13RA1) on non-lymphoid and tumor cells." (PMID 39941924, 2025). "While we did not test DABIL‐4 tumors against IL‐4R‐negative tumors, these results strongly suggest that the depletion of PMN‐MDSCs and M2‐like macrophages in 4T1 tumor‐bearing mice accounts for a significant degree of DABIL‐4 antitumor efficacy." (PMID 33682324, 2021). "IL-4Rα mRNA expression was significantly higher ranging between 33 and 88% relative fluorescence units (RFU) in tumor specimens (P ≤ 0.001) compared to 12.5–22% in normal/noncancerous bladders specimens." (PMID 25208941, 2014). "A total of 28 specimens, which consisted of 16 tumor specimens and 12 normal/noncancerous bladder specimens obtained from CHTN were analyzed for mRNA expression of IL-4Rα, IL-13Rα1, and IL-2Rγc by real-time RT-PCR assay." (PMID 25208941, 2014).
tumor (continued). "Tumor infiltrating myeloid cells represent 79% and 81% of CD45+ cells and express a similar level of IL-4Rα in the presence or in absence of T cells respectively." (PMID 21633700, 2011). "Total human CD11b+ myeloid cells were purified from the tumor or spleen of HSC-NOG-hIL-6 Tg mice or HSC-NOG non-Tg mice, as we could not obtain sufficient numbers of TAM-like cells when we gated HLA-DRlo/− IL-4Rα+ CD163+ CD68+ cells." (PMID 29456539, 2018). "Likewise, several receptor genes (e.g. IL4R, INFAR/INFGR, PTCH/SMO) were consistently expressed by tumor cells and/or TAMs, but ligand expression was not detectable." (PMID 27215396, 2016). "Although IL4Rα-negative MDSC had lower Arg-1 and NOS2 expression before and after chemoradiotherapy, the possibility remains that they may transform into more suppressive cells upon entering the tumor microenvironment." (PMID 37554225, 2023).
infection (116 papers, 2008 to 2025). The state of being infected such as from the introduction of a foreign agent such as serum, vaccine, antigenic substance or organism. "Decreased IL-4Rα positive macrophage recruitment to a site of injury or infection has been linked to the inability to promote IL-4 signalling via IL-4Rα and impairment in induction of IL-4Rα on microglia is noted as a contributing factor to reduced recovery." (PMID 40977748, 2025). "An IL-4Rα-independent mechanism of Th2 differentiation has also been observed in IL-4Rα-deficient BALB/c mice after infection with L. major." (PMID 39830895, 2024). "The IL-4Rα pathway, a common receptor for IL-4 and IL-13 signaling, is essential in generating anti-inflammatory responses and mediating susceptibility to infection by Leishmania parasites causing CL in mice." (PMID 35154068, 2021). "Female BALB/c mice deficient for IL-4Rα on CD11c+ DCs had similar numbers of parasites in their lesions and pLNs compared to their littermate controls at week 8 post-infection (p.i)." (PMID 35154068, 2021). "Since, opposite sexes have been found to differ in the intensity, prevalence, and pathogenesis in various infections including CL and in relation to IL-4Rα deletion, we compared male and female mice deficient for the IL-4Rα on DCs." (PMID 35154068, 2021). "Together, these observations support the concept that asthmatics have an augmented risk of morbidity and mortality related to pH1N1 infection, and that this can be abrogated through IL-4Rα-targeted immunotherapy." (PMID 33653328, 2021). "Previous studies using the N. brasiliensis model in IL-4Rα–deficient animals or IL-4/IL-13-double–deficient mice did not distinguish between the relative roles of IL-4 and IL-13 during infection." (PMID 34127548, 2021). "For example, fully immunocompetent BALB/c mice die from infection with certain strains of Leishmania, whereas immunocompetent C57BL/6 mice and putatively immunodeficient BALB/c interleukin-4 receptor deficient mice can cope with infection." (PMID 34203900, 2021). "Chen and colleagues found that neutrophil infiltration into the lungs upon infection of mice with the helminth Nippostrongylus brasiliensis was associated with IL-4R signaling." (PMID 31708926, 2019). "This pattern was repeated on day 60 post-infection, (e.g., p < 0.0001 for global IL-4Rα−/− mice vs. CD4+ T cell-specific IL-4Rα-deficient mice)." (PMID 31475014, 2019). "Both CD4+ T cell specific IL-4Rα deficient mice and wild-type control mice produced comparable amounts of IgE on days 30 and 56 post-infection." (PMID 31475014, 2019). "Granuloma formation in livers of L. donovani infected mice was assessed at days 15, 30, and 56 post-infection in CD4+ T cell specific IL-4Rα deficient (LckcreIL-4Rα−/lox), wild-type littermate control (IL-4Rα−/lox) and global IL-4Rα−/− BALB/c mice." (PMID 31475014, 2019). "Consistent with this concept, blockade of Ym1 during the adaptive stage of infection prevented efficient lung repair and delivery of Ym1 to IL-4Rα-deficient mice rescued their failure to rapidly repair." (PMID 30500858, 2018). "By day 6 post-infection, a time coinciding with adaptive immunity and an established type 2 response, both RELMα and Ym1 expression was significantly reduced in IL-4Rα-deficient mice compared to BALB/c wild-type mice." (PMID 30500858, 2018). "Wild-type mice are susceptible to infection with the C. neoformans strain 18415,20, while IL-4Rα-deficient mice, characterized by a dominant Th1 and Th17 response, are resistant to pulmonary cryptococcal infection." (PMID 29422616, 2018). "Collectively, the data indicate that despite a change in the site/route of infection and the dose of parasites, KRT14cre IL-4Rα−/lox BALB/c mice remain susceptible to L. major and remain unaffected by the abrogated IL-4Rα signaling on keratinocytes." (PMID 30275010, 2018).
infection (continued). "Both severe-combined and IL-4Rα-specific deficiencies rendered mice susceptible to chronic B. malayi adult-stage infections at +35dpi with significant differences apparent in the control of larval establishment from +14dpi." (PMID 29547639, 2018). "KRT14cre IL-4Rα−/lox BALB/c mice were susceptible to infection, showing progressive footpad swelling and parasite loads, characteristic of genetically susceptible BALB/c mice." (PMID 30275010, 2018). "In support of this, via transcript analysis of peritoneal cells we identified a significant reduction in CCL11 (eotaxin 1) expression in IL-4Rα deficient mice 6 days after infection with BmL3." (PMID 29547639, 2018). "Interrupting IL-4Rα mediated signaling prior to secondary infection in inducible IL-4Rα deficient mice diminished the recall of protective memory response." (PMID 28651009, 2017). "Initial control of L. major during the acute phase of infection in IL-4−/−-deficient mice and IL-4Rα−/−-deficient BALB/c mice is equivalent, with both strains of mice showing reduced footpad swelling, parasite loads and type 1 antibody responses." (PMID 29176972, 2017). "Liver egg burden was similar between the different groups, ruling out a differential level of infection as the cause of the observed diminished type 2 responses in iCre-/+IL-4Rα-/lox Tam6 and IL-4Rα-/- mice." (PMID 28827803, 2017). "The bacillary burden at 4 weeks after infection was significantly increased in macrophage cell-specific IL-4Rα deficient mice when compared to wild-type mice." (PMID 25790379, 2015). "Because LysMCre-mediated deletion of the floxed IL-4Rα gene is relatively inefficient 57 we predicted that chronic IL-4 exposure was causing an outgrowth of IL-4Rα sufficient macrophages, such that by day 60 post infection all macrophages were wildtype." (PMID 25319331, 2014). "We conclude that i) IL-4Rα−/− mice are initially more susceptible to infection with C. neoformans as shown by stronger fungal growth within the first two weeks of infection." (PMID 24475277, 2014). "Susceptible WT BALB/c and IL-4Rα-/lox littermate control mice developed progressive footpad swelling after infection with both strains, with increased parasite burdens in the infected footpads and draining LN." (PMID 24204259, 2013). "IL-4-deficient (IL-4−/−), as well as IL-4 receptor alpha (IL-4Rα)-deficient BALB/c mice are resistant to infection with L. major." (PMID 22802978, 2012). "Compared to that observed in WT mice, infection of IL-4Rα-/- mice by RSV that impaired AAM development caused worse lung pathology and thus a protective role of these cells was suggested." (PMID 21246055, 2011). "Conversely CD4+ T cell specific (LckcreIL-4Rα−/lox) IL-4Rα−/− mice are more susceptible than global IL-4Rα−/− mice to infection with L. mexicana, indicating a role for an IL-4/IL-13 responsive non CD4+ T cell population in early susceptibility." (PMID 21245915, 2011). "However, it is noteworthy that despite the general association of IL-4Rα with Th2-mediated disease progression, during the early stage of infection, the IL-4Rα signaling pathway enhances the host defense through a dual mechanism." (PMID 41017910, 2025). "Moreover, IL-4Rα -deficient and IL-4Rα sufficient BMDCs produced similar levels of IL-12p70 and IL-10 during infection hence suggesting that IL-4-mediated DC instruction was not impaired in CD11ccreIL-4Rα-/lox." (PMID 35154068, 2021). "The low levels of type 1 antibodies, namely, IgG2a and IgG2b, exhibited in CD11ccreIL-4Rα-/lox and IL-4Rα-/lox mice also further demonstrate the systemic inability of these mice to control the infection as type 1 antibodies have been associated with parasite clearance." (PMID 35154068, 2021). "We thus examined IL-4Rα−/− mouse susceptibility to immature (prefecund) adult B. malayi starting at 5 wk postinfection when the majority of wild-type (WT) mice have cleared infections at a point preceding adult development." (PMID 32571840, 2020).